ERO1A (endoplasmic reticulum oxidoreductase 1 alpha)
Diseases named in the same sentence as ERO1A in open-access papers (continued):
Sharing a sentence is not in itself a finding about the gene and the disease.
pancreatic cancer (12 papers, 2017 to 2022). "Among these proteins, the oxidoreductase enzyme ERO1α was highly sensitive to induction by hypoxia stress across a range of different pancreatic cancer cell lines and was associated with particularly poor prognosis in human patients." (PMID 31666928, 2019). "Consistent with this concept, our data confirmed that ERO1α-deficient pancreatic cancer cells displayed negligible ability to form tumors in vivo, thus implicating ERO1α as a potential novel target for cancer therapy in human patients." (PMID 31666928, 2019). "We then infected human pancreatic cancer cells with Cas9-expressing lentiviral vectors in order to disrupt the ERO1α gene and used Sanger sequencing to verify mutation at the predicted site." (PMID 31666928, 2019). "However, we also identified that hypoxic stress induces pancreatic tumor cell expression of the oxidoreductase enzyme ERO1α, which displayed a clear association with poor survival statistics mined from patient gene expression databases." (PMID 31666928, 2019). "Remarkably, ERO1A is a prognostic marker and a promising target in different types of cancer, such as non-small cell lung cancers, osteosarcoma, pancreatic cancer." (PMID 34360775, 2021). "In pancreatic cancer cells, signaling through ERO1A is involved with metabolic reprogramming to glycolysis, which reduces the flux through PDHC." (PMID 34360775, 2021). "These analyses also indicated that ERO1α is expressed at elevated levels in pancreatic cancers relative to adjacent healthy tissues from the same patient, and that high tumor expression of this enzyme is significantly correlated with short survival duration." (PMID 31666928, 2019). "Together, these data strongly indicate that under hypoxic conditions, pancreatic tumor cells significantly upregulate the enzyme ERO1α, which is a critical determinant of pancreatic cancer patient survival." (PMID 31666928, 2019). "In order to test the function of ERO1α in pancreatic cancer cells, we used a CRISPR/Cas9 approach to delete the corresponding gene and assessed the impact on oncogenic potential in a range of different assays." (PMID 31666928, 2019). "To better understand the role of ERO1α in pancreatic cancer progression, we next deleted the corresponding gene using CRISPR/Cas genome editing technology and assessed the impact on tumor cell function both in vitro and in vivo." (PMID 31666928, 2019). "Together, these data indicate that ERO1α is potential prognostic biomarker and novel drug target for pancreatic cancer therapy." (PMID 31666928, 2019). "Together, these data indicate that hypoxia-induced enzyme ERO1α is a novel therapeutic target in pancreatic cancer and a potential biomarker for enabling earlier disease detection and better prediction of clinical course in human patients." (PMID 31666928, 2019). "Accordingly, genetic deletion of ERO1α inhibited pancreatic tumor proliferation, colony formation, and cellular ROS production in vitro, while cell transfer into a mouse xenograft model confirmed a profound reduction in tumor development in vivo." (PMID 31666928, 2019). "In particular, the oxidoreductase protein ERO1α displayed an unweighted meta z score of 7.67 for all cancer types, thus strongly implicating this enzyme as a key determinant of poor clinical outcome in human pancreatic cancer." (PMID 31666928, 2019). "Given that HIF-1α expression is known to be controlled by reactive oxygen species (ROS), we next assessed whether the generation of these mediators might represent an important mechanism by which ERO1α influences pancreatic cancer progression." (PMID 31666928, 2019). "Indeed, further analysis of ERO1α expression patterns in relevant GEO databases, enabled us to confirm that a range of different pancreatic cancer cell lines strongly upregulate ERO1α under hypoxic conditions." (PMID 31666928, 2019).
pancreatic cancer (continued). "We have illustrated that ERO1A may play critical roles in pancreatic cancer progression and represent shorter overall survival and worse clinical prognosis." (PMID 28881752, 2017). "Specifically, our data reveal that the oxidoreductase enzyme ERO1α is a major proliferation regulator in pancreatic cancer cells both in vitro and in vivo, hence this protein may constitute a useful diagnostic marker of tumor progression and possible new therapeutic target in pancreatic malignancy." (PMID 31666928, 2019). "Accordingly, western blot analysis of ERO1α expression in the treated cells confirmed that our gene disruption strategy achieved complete knockout of ERO1α protein, so we proceeded to test whether pancreatic tumor cell proliferation rates differed between WT and ERO1α-KO clones." (PMID 31666928, 2019). "Since ERO1α enzyme activity is known to generate reactive oxygen species (ROS) which directly regulate the hypoxia response through transcription factor HIF-1α, we next assessed whether ROS generation might underpin the influence of ERO1α on pancreatic cancer progression." (PMID 31666928, 2019). "Seven GRGs: CDK1, DSC2, MET, PYGL, CHST12, ERO1A, and SLC35A3 were selected to construct the prognostic model related to the overall survival rate of patients with pancreatic cancer." (PMID 33912561, 2021). "Expression analysis further revealed that CDK1, DSC2, ERO1A, MET, PYGL, and SLC35A3 were highly expressed in pancreatic cancer while CHST12 was highly expressed in normal pancreatic tissues." (PMID 33912561, 2021). "CDK1, DSC2, ERO1A, MET, PYGL, and SLC35A3 were highly expressed while CHST12 was decreased in pancreatic cancer." (PMID 33912561, 2021). "We selected the marker genes (ADM, ERO1A, ENO2, BNIP3, and UPP1) of CAF-C2 to detect their expression in human pancreatic CAF-stellate cell (CAF118), human pancreatic cell (HPC-Y5), and human pancreatic cancer cell line." (PMID 36544710, 2022). "While ERO1α-KO pancreatic cancer cells were morphologically indistinguishable from their wild-type counterparts, tumor proliferation and colony-forming potential were significantly reduced in the absence of this enzyme." (PMID 31666928, 2019). "Unlike their WT counterparts, ERO1α-KO tumors displayed little to no growth over a 24–72 h culture period, and colony formation was reduced by as much as 50%, suggesting that ERO1α deletion significantly reduces the replicative capacity of pancreatic cancer cells." (PMID 31666928, 2019).
colorectal cancer (9 papers, 2017 to 2024). A primary or metastatic malignant neoplasm that affects the colon or rectum. "Recently, ERO1α has also been shown to have a role in post-translational modification of β1 integrin in colorectal cancer cell when under hypoxic conditions." (PMID 33615311, 2020). "Our study has established a previously unrecognized link between ERO1α expression and integrin activation, and thus provides new evidence for the effectiveness of ERO1α-targeted therapy for colorectal carcinoma." (PMID 28839225, 2017). "ERO1α−/− (KO) clones were developed in HCT116, a human colorectal carcinoma cell line, by using the CRISPR/Cas9 system." (PMID 28839225, 2017).
hepatocellular carcinoma (7 papers, 2014 to 2025). A malignant tumor that arises from hepatocytes. "Mechanistically, we showed that ERO1α prompted angiogenesis, migration, and invasion of hepatoma cells via the S1PR1/STAT3/VEGF-A signaling pathway both in vitro and in vivo." (PMID 30377291, 2018). "In addition to the finding that ERO1α deficiency can inhibit angiogenesis by increasing N-glycosylation of VEGFA, ERO1α also induces the S1PR1/STAT3/VEGF-A signaling pathway triggers tumor migration, angiogenesis, invasion, and EMT of hepatocellular carcinoma." (PMID 41333024, 2025). "Interestingly, overexpression of ERO1α tends to have a worse prognosis in multiple cancer indications; multiple myeloma, breast and hepatocellular carcinoma, as well as lung, esophageal, diffuse B-cell lymphoma, and others according to The Cancer Genome Atlas (TCGA) and The Protein Atlas." (PMID 33615311, 2020). "Studies have shown that ERO1α serves as a central regulator of EMT enhancing invasion and metastasis in cancers such as hepatocellular carcinoma." (PMID 41333024, 2025). "However, the clinical relevance of ERO1α and its molecular mechanisms underlying tumor progression have not been determined for hepatocellular carcinoma (HCC)." (PMID 30377291, 2018). "Furthermore, our results reveal that ERO1α prompted the migration, invasion, angiogenesis, EMT, and lung metastasis of hepatoma in vitro and in vivo, suggesting that ERO1α upregulation was involved in HCC progression." (PMID 30377291, 2018). "Ero1a (endoplasmic reticulum reductase 1 alpha) is a negative prognostic marker in a variety of tumor types, including in EGFR-mutated forms of non-small cell lung cancer, colon cancer, and hepatocellular carcinoma." (PMID 41009560, 2025).
triple-negative breast carcinoma (7 papers, 2017 to 2025). An invasive breast carcinoma which is negative for expression of estrogen receptor (ER), progesterone receptor (PR), and human epidermal growth factor receptor 2 (HER2). "This is corroborated by clinical data in triple negative breast cancer cases, where the expression of ERO1α is correlated with the number of blood vessels." (PMID 41333024, 2025). "Here, we report the upregulation of ERO1A in a cohort of aggressive triple-negative breast cancer (TNBC) patients in which ERO1A levels correlate with a higher risk of breast tumor recurrence and metastatic spread." (PMID 39962052, 2025). "The highest ERO1α expression levels were observed in basal-like cell lines, particularly in triple-negative breast cancer (TNBC) cells such as MDAMB231." (PMID 41226317, 2025). "In clinical cases, we observed that the expression of ERO1-α in triple negative breast cancer was related to the expression of PD-L1." (PMID 28160557, 2017). "Notably, ERO1A is overexpressed in triple-negative breast cancer (TNBC), where it supports tumor growth and adaptation to hypoxia, and in SEPN1-related myopathy, a rare congenital muscle disorder linked to ER and oxidative stress." (PMID 41270850, 2025). "In this study, we found by using triple negative breast cancer MDA-MB-231 cells and MDA-MB-468 cells that overexpression of ERO1-α protein resulted in augmented expression of PD-L1." (PMID 28160557, 2017).
colon cancer (6 papers, 2017 to 2025). "The expression levels of LAMB3 and ERO1A were assessed by IHC in tissue array 1, which includes 90 rectal cancer samples, and tissue array 3, which includes 30 colon cancer samples." (PMID 36209225, 2022). "MiR-182-5p overexpression strikingly suppressed oncogenicity of colon cancer cells, and ERO1A is a prognostic marker for non-small cell lung cancer." (PMID 36289596, 2022). "Here, we investigated the cell biological roles of ERO1α in the human colon-cancer cell line HCT116." (PMID 28839225, 2017).
non-small cell lung carcinoma (5 papers, 2020 to 2025). A group of at least three distinct histological types of lung cancer, including non-small cell squamous cell carcinoma, adenocarcinoma, and large cell carcinoma. "Combined expression of protein disulfide isomerase and endoplasmic reticulum oxidoreductin 1-α (ERO1A) is a poor prognostic marker for non-small-cell lung cancer." (PMID 33414898, 2020).
pancreatic ductal adenocarcinoma (5 papers, 2017 to 2024). An infiltrating adenocarcinoma that arises from the epithelial cells of the pancreas. "For example, Zhang and colleagues reported that ERO1α was significantly overexpressed and promoted cell proliferation and tumor growth in pancreatic ductal adenocarcinoma (PDAC)." (PMID 38610018, 2024). "ERO1A has previously been reported to be induced by hypoxia in cervical cancer cell lines, and it was considered to be a predictive biomarker in pancreatic ductal adenocarcinoma." (PMID 28796930, 2017). "In the present study, we determined the feasibility of three genes (ERO1A, OSBPL3 and IFI44L) working as potential biomarkers in pancreatic ductal adenocarcinoma (PDAC)." (PMID 28881752, 2017).
breast tumor (4 papers, 2022 to 2025). "Here, immunofluorescence on human breast tumor samples indicate that ERO1A is more upregulated in aggressive and highly proliferative TNBC than in other breast tumor types, suggesting a critical role of ERO1A in this still incurable breast tumor." (PMID 39962052, 2025). "However, a high EIF2AK3:ERO1A ratio predicts a better outcome, indicating cooperation of PERK with the ERO1 pathway in breast tumours." (PMID 35853086, 2022).
gastric cancer (4 papers, 2017 to 2023). A primary or metastatic malignant neoplasm involving the stomach. "Recent studies demonstrated that miR-218-5p served as a tumor suppressor to inhibit tumor growth and development by targeting endoplasmic reticulum oxidoreductase one alpha (ERO1A), COMMD8, CDK6, and EGFR in lung, liver, and gastric cancer." (PMID 36831545, 2023).
heart failure (4 papers, 2017 to 2025). Inability of the heart to pump blood at an adequate rate to meet tissue metabolic requirements. "Transverse aortic constriction (TAC) surgery in wild-type (WT) mice and ERO1α ablation mice confirmed that deletion of ERO1α protects mice from progressive heart failure." (PMID 36588561, 2022). "In conclusion, ERO1α may represent a promising therapeutic target for mitigating arrhythmias and enhancing cardiac function in heart failure." (PMID 41333024, 2025). "In homozygous ERO1α mutant adult cardiomyocytes, the peak amplitude of calcium transients was reduced and protected mice lacking ERO1α against progressive heart failure in a transaortic constriction model." (PMID 41333024, 2025). "To further identify the mechanism by which Aggf1 haploinsufficiency augments cardiac hypertrophy and heart failure, we analyzed CHOP and other ER stress signaling markers BiP, ERO1α, Puma, DR5, ATF4, cATF6, p-eIF2α, phosphorylated PERK (p-PERK), and sXBP1 using western blot analysis." (PMID 28743963, 2017).
cholangiocarcinoma (3 papers, 2021 to 2025). A carcinoma that arises from the intrahepatic biliary tree (intrahepatic cholangiocarcinoma) or from the junction, or adjacent to the junction, of the right and left hepatic ducts (hilar cholangiocarcinoma). "According to Yan and colleague, the expression of ERO1A is increased in cholangiocarcinoma and its overexpression predicts poor prognosis of patients." (PMID 38106991, 2023).
diabetes (3 papers, 2013 to 2025). "This reviews provide an in depth summary regarding ERO1α in various disease processes, including cardiovascular diseases, diabetes, and cancer." (PMID 41333024, 2025). "Studies have shown that CHOP knockout can reduce the expression of ERO1α, alleviate oxidative stress, improve islet β cell function and promote cell survival in a variety of diabetic mouse models, thereby slowing the progression of T2DM." (PMID 41333024, 2025). "In the setting of diabetes, CHOP deficiency suppressed pancreatic beta cell apoptosis, and this protection was associated with decreased ERO1α, suppression of oxidative-stress markers and induction of anti oxidant genes." (PMID 24223941, 2013). "Therefore, increasing the expression of ERO1α is a possible strategy for the treatment of diabetes and diabetic insulin resistance." (PMID 41333024, 2025). "Under pathological conditions including hypoxia and metabolic disorders, dysregulated ERO1α expression is closely related to the occurrence and development of various diseases such as cancer, neurodegenerative diseases, cardiovascular disorders, diabetes, and inflammatory conditions." (PMID 41333024, 2025).
glioma (3 papers, 2022 to 2025). A benign or malignant brain and spinal cord tumor that arises from glial cells (astrocytes, oligodendrocytes, ependymal cells). "The predominant majority of rat glioma 101.8 tumor cells expressed Cadm2, Cdkn1b, and Ero1a." (PMID 41009560, 2025).
ischemic stroke (3 papers, 2015 to 2025). A stroke disorder caused by obstruction of blood flow to the brain, due to thrombotic (local blood clot formation) or embolic (due to a blood clot or other material traveling from another site) event. "ERO1α, expressed by the ero1a gene, is activated by hypoxia-inducible factor 1, as shown in a rat model of ischemic stroke." (PMID 36588561, 2022). "The deletion of ERO1α or inhibition with a small-molecule inhibitor B12-5 (IC50 = 7.9 μM) results in reduced infarct volume and improved neurological outcomes in ischemic stroke models, indicating that targeting ERO1α may offer potential benefits in stroke treatment." (PMID 41333024, 2025). "In an in vivo and in vitro model of ischemic stroke, we provide evidence that CHOP and Ero1-α of the UPR are possible therapeutic targets in ischemic injury." (PMID 25989620, 2015). "In an in vitro and in vivo model of ischemic stroke, we investigated whether hypothermia regulates the unfolded protein response of CHOP and Endoplasmic reticulum oxidoreductin-α (Ero1-α), because Ero1-α is suggested to be a downstream CHOP target." (PMID 25989620, 2015).
leukemia (3 papers, 2017 to 2025). A malignant (clonal) hematologic disorder, involving hematopoietic stem cells and characterized by the presence of primitive or atypical myeloid or lymphoid cells in the bone marrow and the blood. "Moreover, apoptosis of Jurkat leukemia T cells, which express PD-1, induced by tumor PD-L1 was inhibited when ERO1-α was depleted." (PMID 28160557, 2017). "Moreover, to demonstrate the consequences of ERO1α-mediated overexpression of PD-L1 for anti-tumor immunity, authors showed that coculture of Jurkat leukemia T cells with ERO1α-expressing cells resulted in enhanced apoptosis of T cells compared to ERO1α knock-down cells." (PMID 41226317, 2025).
melanoma (3 papers, 2016 to 2023). A malignant, usually aggressive tumor composed of atypical, neoplastic melanocytes. "Taken together, these results suggest that ERO1A expression is associated with the efficacy of ICI treatment in patients with NSCLC and melanoma." (PMID 37769655, 2023). "To further investigate whether ERO1A expression was associated with better clinical outcomes in patients treated with immunotherapy, we collected transcriptome profiling combined with corresponding clinical data of ICI-treated patients with NSCLC (GEO: GSE190265) and melanoma (ENA: PRJEB23709)." (PMID 37769655, 2023). "We observed that δ-TT increases the expression of ERO1α in A375, but not in BLM, melanoma cells; on the other hand the expression of PDI was unaffected by the treatment in both cell lines." (PMID 27461002, 2016).
acute liver failure (2 papers, 2019 to 2025). Rapid deterioration of liver function causing encephalopathy and coagulopathy. "As a target of CHOP, the CHOP/ERO1α pathway underlies hepatocellular apoptosis during acute liver failure (ALF) and ER stress-induced apoptosis in macrophages." (PMID 31766455, 2019). "In addition, ERO1α is also associated with Hcy-induced nonalcoholic fatty liver disease, liver injury, and acute liver failure." (PMID 41333024, 2025). "Also in acute liver failure, CHOP increases ROS levels and promotes ERS by activating ERO1α, thereby exacerbating liver injury during acute liver failure." (PMID 41333024, 2025).
atherosclerosis (2 papers, 2025). A disease characterized by the build-up of fatty material and calcium deposition in the arterial wall resulting in partial or complete occlusion of the arterial lumen. "In the context of atherosclerosis, the development of vulnerable plaques in atherosclerosis promoted by Hcy upregulates ERO1α expression and activates ERS-dependent macrophage apoptosis." (PMID 41333024, 2025).